CXCL12 (C-X-C motif chemokine ligand 12)
Diseases named in the same sentence as CXCL12 in open-access papers (continued):
Sharing a sentence is not in itself a finding about the gene and the disease.
cancer (continued). "In terms of mechanism, further investigation revealed that CAF‐S1 fibroblasts promoted BC cell migration and EMT initiation in cancer cells in a CXCL12‐ and TGF β‐dependent manner." (PMID 38158643, 2024). "Several pathological processes, such as cancer and inflammatory diseases, are implicated in aberrant CXCR4/CXCL12 signaling." (PMID 39070795, 2024). "Based on their observations that cancer cells in these tumors are coated with CXCL12, the researchers proposed a possible explanation for this lack of response." (PMID 39070795, 2024). "CAFs derived from ASCs secrete factors like TGF-β, IL-6, and CXCL12 that can trigger the EMT in cancer cells, enhancing their migratory and invasive potential." (PMID 39519109, 2024). "In contrast, CXCL12 expression was relatively low in cancer tissue in cases with only a few lymphocyte aggregates." (PMID 38767772, 2024). "CXCL12, released by perivascular fibroblasts, lures motile TAMs and cancer cells toward the vasculature." (PMID 39068459, 2024). "To gain insights into the relevance of the CXCL12/HMGB1 heterocomplex in cancer cell activities, we evaluated their capability to promote wound healing, migrate and invade the extracellular matrix." (PMID 38803493, 2024). "The present work shed light on the activity of the CXCL12/HMGB1 heterocomplex on cancer cells, particularly those with a high metastatic potential and a functional thioredoxin system." (PMID 38803493, 2024). "Numerous studies employed CXCR4 inhibitors to suppress the CXCL12/CXCR4 signals for treating cancer." (PMID 39070795, 2024). "By interacting with its receptor CXCR4, CXCL12 promotes migration, invasion, and angiogenesis in cancer cells, a chemokine abundantly expressed in the TME." (PMID 39070795, 2024). "The FAP+CAFs were discovered to utilize the CXCR4/CXCL-12 axis to effectively exclude CD8+ T cells from the region containing cancer cells by releasing CXCL-12, ultimately preventing the CD8+ T cells from reaching the TME." (PMID 39609700, 2024). "Targeting CXCR4 with R54 reverts CXCL12-induced cancer cell growth in presence of CDDP/PTX, particularly in OVCAR8 and IGROV1 treated with PTX potentiating the effect of chemotherapeutic agents." (PMID 39700131, 2024). "Expression of CXCL12 was sharply increased after the occurrence of cancer pain, and it was positively correlated with the expression of Iba1." (PMID 39641645, 2024). "The CXCL12/CXCR4 axis plays a critical role in promoting cancer cell proliferation, migration, invasion, angiogenesis and metastasis." (PMID 39195299, 2024). "In the present study, we analyzed further the influence of flow rate and CXCL12 on the directional distribution of cancer cells, both with and against the flow direction." (PMID 39715221, 2024). "Based on the immunohistochemistry technique, investigators concluded that CXCL12 and its receptor levels depended on the amount of cancer cells." (PMID 38673838, 2024). "Since the CXCL12/CXCR4 axis plays a crucial role in cancer and AD pathogenesis, inhibiting it seems like a promising therapeutic approach." (PMID 39070795, 2024). "CXCR4 and its endogenous ligand C-X-C motif chemokine 12 (CXCL12) play a crucial role in various immune diseases and cancer progression." (PMID 39162901, 2024). "The CAF secretome induces the proliferation of cancer cells via the secretion of cytokines, such as CXCL-12, EGF, HGF; with energy-rich metabolites, such as ketones, lactate and glutamine; and via exosomes." (PMID 39696386, 2024). "In summary, lactate secreted by cancer cells can promote the transformation of fibroblasts into iCAFs and the expression of CXCL12, possibly via the PI3K-Akt-HIF1A axis." (PMID 38287007, 2024). "Other studies found that intrathecal injection of CXCL12 neutralizing antibody alleviated cancer pain and reduced Iba1 levels after TCI treatment." (PMID 39641645, 2024).
cancer (continued). "The c04_CXCL12 subgroup displayed characteristics of both antigen‐presenting cancer‐associated fibroblasts (apCAFs), marked by CD74 and HLA‐DRA, and immune‐related cancer‐associated fibroblasts (iCAFs), indicated by CXCL14 and CXCL12." (PMID 39716897, 2024). "The mechanism leading to an avoidance of cancer cells rapid proliferation by CXCL12 and, thus chemotherapy treatment is, so far, poorly understood." (PMID 37182144, 2023). "The receptor and its chemotactic ligand, CXCL12, function to regulate cell migration and are upregulated in various cancers, including MF." (PMID 37175780, 2023). "As a target gene of miR-31, the downregulation of C-X-C Motif Chemokine Ligand 12 (CXCL12) was of great significance in the development of precancerous lesions to cancer." (PMID 36902423, 2023). "Taken together, these results suggest that the LPA1 activation inhibits CXCL12-induced migration in cancer cells that endogenously express both CXCR4 and LPA1." (PMID 37749552, 2023). "Extensive research has been conducted on the role of cancer-associated fibroblasts (CAFs) in solid tumors, particularly in relation to their production of soluble factors such as IL-1α, IL-1β, CXCL1, CXCL12, G-CSF, and IL-6." (PMID 37880682, 2023). "After docetaxel and androgen deprivation treatment, prostate cancer cells secreted more CXCL12 via TAMs,386 which helped cancer cells survive and reduced their sensitivity to chemotherapy by activating CXCR4." (PMID 37211559, 2023). "The CXCR4/CXCL12 axis has been extensively studied and shown to promote cancer cell migration, invasion, and metastasis in a variety of cancers, such as lung cancer, liver cancer, breast cancer, prostate cancer, and esophageal cancer." (PMID 36308553, 2023). "This is consistent with our finding that CXCL12 is expressed in cancer cells and muscle cells but is less abundantly expressed in fibroblasts." (PMID 36300800, 2023). "CXCL12 secreted by CAFs positive for α-smooth muscle actin (α-SMA) thus promotes the proliferation of cancer stem cells through interaction with its receptor CXCR4." (PMID 37174001, 2023). "This differentiation occurred through cancer cell induced TGFβ-dependent upregulation of CXCR4 in monocytes while CXCL12 expressed by perivascular fibroblasts attracted these motile TAMs toward the blood vessels, bringing motile cancer cells with them." (PMID 37261345, 2023). "Chemotaxis plays an important role in the migration of cancer cells and subsequent metastasis toward chemotactic molecules such as CXCL12 and EGF." (PMID 36829763, 2023). "By increasing the expression of growth factors such as PDGF and TGF-β, ROS regulates the communication between cancer cells and fibroblasts, subsequently triggering the release of chemokines such as CXCL12." (PMID 37007004, 2023). "The hyperactivation of CXCL12/CXCR4 in cancer cells compared to their normal counterparts makes this axis a promising target for targeted therapy of cancer cells." (PMID 37966614, 2023). "CXCL12 functions critically as chemoattractant in cancer progression and invasion of malignant tumours." (PMID 37162544, 2023). "Regarding other types of cancer, the best-characterized cytokines that mediate MSCs homing to tumors include CXCL12, IFN-γ, IL-6, IL-8 and TNF, as well as growth factors such as TGF-β, HGF, PDGF and VEGF." (PMID 37563650, 2023). "There is limited information in the cancer literature comparing CXCL12 TICs as biomarker with our results." (PMID 37966614, 2023). "Cxcl12 is a multi-effect chemokine that participates in the regulation of tissue homeostasis, immune surveillance, inflammatory response, and cancer development." (PMID 37533129, 2023). "CXCR4 is a specific chemokine receptor of CXCL12, which is highly expressed on human progenitor cells and stem cells, including cancer stem cells." (PMID 36308553, 2023). "Other factors promoting cancer progression and chemoresistance are chemokines (i.e., SDF-1/CXCL12) and cytokines, such as interleukine-6 (IL-6)." (PMID 37173963, 2023).
cancer (continued). "Cancer cells interact with the chemokine/chemokine receptor system to escape immune attack partially by coating themselves with CXCL12." (PMID 37359565, 2023). "This review aims to provide an overview of the progress made in understanding the signaling axis of CXCL12 and its receptors in various types of cancer." (PMID 37497001, 2023). "Generally, CAFs promote the malignant progression of cancer cells by secreting cytokines, chemokines, and proangiogenic factors, including CXCL12, TGF-β1, VEGF, PDCF, IL-6 and CXCL16." (PMID 38057830, 2023). "Overexpression of TSTA3 abnormally activated CXCR4/CXCL12 axis, thereby mediating cancer cell adhesion, metastasis and immune escape." (PMID 37986192, 2023). "LPA or alkyl-OMPT inhibited CXCL12-induced migration in various cancer cells that endogenously express both CXCR4 and LPA1." (PMID 37749552, 2023). "CAF-S1 activates the EMT of breast cancer cells through CXCL12 and TGFβ pathways, mainly playing a role in stimulating cancer cell migration." (PMID 36624542, 2023). "Our findings suggest that curcumin has great value as an anticancer agent that can remodel breast TME by limiting ADMSC-cancer interaction through regulation of the CXCL12/CXCR4 axis." (PMID 38004606, 2023). "Activation of CXCR4 in BC cells by its ligand, CXCL12, promotes chemotaxis and migration of cancer cells towards CXCL12-rich environments, which coincidentally represent the main sites for BC metastasis, namely the bones, lymph nodes, lungs, and liver." (PMID 37253733, 2023). "Costimulation of CXCR4 and HRH1 synergistically increases calcium flux and CXCL12-induced cell migration in various cancer cells that express CXCR4 and HRH1 endogenously." (PMID 36732336, 2023). "In contrast, downregulation of CXCL12 and upregulation of SIX4, the two unique hub genes in MCF7-ERβ2 cells, are reportedly consistent with cancer-promoting effects and are linked to poor prognosis." (PMID 36835157, 2023). "While some gastric and colorectal carcinoma cells can produce CXCL12 themselves, the quantitative largest source in PDAC is derived from cancer-associated fibroblasts (CAFs)." (PMID 37834436, 2023). "Over the last years, different research groups started investigating the use of hydrogels or scaffolds loaded with CXCL12 for local delivery of this chemokine to promote injury repair, wound healing, bone repair, and for cancer treatment." (PMID 36725964, 2023). "Given that combinations of biomarkers are likely needed due to the multifactorial nature of cancer–immune interactions, we further combined PD-L1 status with the CXCL12 level in an attempt to distinguish DCB and NDB patients." (PMID 37359565, 2023). "Accordingly, a comprehensive understanding and targeting of CXCL12/CXCR4/NF-κB/SHH signaling holds great importance in treating cancer." (PMID 38004606, 2023). "We also found that the effects of a specific cancer treatment with the blockade of CXCL12 differed between sexes." (PMID 36980700, 2023). "Tissues that constitutively express CXCL12 are the main sites of metastasis for CXCR4-expressing cancer cells." (PMID 36614308, 2023). "The interaction of CXCR4 and its ligand stromal-derived factor 1α (SDF-1α, also known as CXCL12) mainly secreted by stromal cells promotes several aspects of cancer progression including angiogenesis, metastasis, relapse, drug resistance, and survival." (PMID 36762192, 2023). "Owing to its role in cancer metastasis and progression, the CXCL12/CXCR4 axis is an important target for cancer therapy." (PMID 38004606, 2023). "It was also detected that HIC1 expression was positively related to several immunestimulators in different cancers, such as CXCL12 and TNFRSF4, and was negatively connected with IL-6R in TGCT." (PMID 37388742, 2023). "By secreting cytokines and chemokines like TGF-β and CXCL12, CAFs prevent the activation and recruitment of T lymphocytes in cancer sites." (PMID 37784082, 2023).
cancer (continued). "A more comprehensive analysis will be necessary to identify cancer cell‐derived factors that induce CXCL12 expression in muscle cells." (PMID 36300800, 2023). "Once cancer cells metastasize to the bone, different chemokine motif ligands (CXCL12, CXCR4, CXCL5, CXCR2) promote breast cancer cell colonization within the bone." (PMID 36674719, 2023). "In gastric cancer, it is observed that the migrated MSCs to the inflammation site of tumor stroma generate CAFs through activating TGF-β and SDF-1α pathways by TGF-β and CXCL12 isolated from cancer cells and the TME or by tumor derived exosomes." (PMID 38022534, 2023). "In fact, the CXCL12/CXCR4 axis is among the most studied chemokine axes in cancer metastasis due to its capacity to support cancer cell proliferation, migration and invasion." (PMID 37198402, 2023). "In agreement with The Cancer Genome Atlas, we found that EN and CXCL12 expression positively correlated in ENKO or blocked mice." (PMID 36646951, 2023). ", TNC can retain CD8+ TIL in cancer stroma by binding CXCL12, which facilitates the progression of BC." (PMID 37784082, 2023). "Among these genes, the chemokine receptor CXCR4 and its ligand CXCL12 were widely reported to be involved in cancer cell survival, proliferation, and migration." (PMID 37908977, 2023). "For example, decreased expression of CXCL12 was associated with unfavorable overall survival (OS) and disease-free survival (DFS) in all types of cancer, whereas CXCR4 was highly expressed in several cancer types." (PMID 37198402, 2023). "Meanwhile, IL‐8 secreted by PTEN‐deficient prostate cancer cells can also augment CAF‐derived CCL2 and CXCL12, leading to increased proliferation and migration of the cancer cells." (PMID 36608258, 2023). "The results demonstrated that CAFs-derived CXCL12 promoted cancer cell migration and invasion and upregulated PDL1." (PMID 38001512, 2023). "Again, CXCL12/CD66b positivity was confirmed to represent an independent favorable RFS predictor in primary cancer biopsies (HR 0.15; 95% CI 0.05–0.43; p = < 0.001, 95% HR 0.13; CI 0.04–0.42; p = 0.001, respectively)." (PMID 37966614, 2023). "When samples were divided based on histological grade, 11 of 13 grade 1 tumors (84.6%), 17 of 26 grade 2 tumors (65.4%), and 2 of 8 grade 3 tumors (25.0%) contained CXCL12‐positive cancer cells (p = 0.021)." (PMID 36300800, 2023). "CXC chemokine receptor 4 (CXCR4) and its ligand CXCL12, both of which are overexpressed in many cancers, play a pivotal role in metastasis." (PMID 37749552, 2023). "According to the immunostimulatory and chemokine genes, CXCL12 is positively correlated with 20 cancers and IL6R is negatively correlated with 29 tumors." (PMID 37671947, 2023). "CXCL12 and its receptor signaling axis are involved in various diseases, including cancer, atherosclerosis 10, Alzheimer's disease 11, diabetes 12, and autosomal dominant polycystic kidney disease." (PMID 37497001, 2023). "The expression levels of CXCL12 and its receptors in cancer tissues differ significantly from those in normal tissues." (PMID 37497001, 2023). "Another study independently confirmed that CXCR4 antagonism with plerixafor (AMD3100) enhances T cell infiltration by releasing trapped CXCR4-expressing T cells in CXCL12-rich stroma before reaching carcinoma cells." (PMID 37966614, 2023). "The overexpression of the CXCL12/CXCR4 complex was found to be a marker for bone metastases in many cancer types." (PMID 36497192, 2022). "Many signaling pathways are involved in cancer progression, and among these pathways, the CXCL12 axis and its two receptors CXCR4 and CXCR7 are well described for many cancers." (PMID 35406582, 2022). "Prrx1-induced soluble factors included IL6, CSF, CCL5, and CXCL12, which promote both cancer progression and wound healing." (PMID 35589735, 2022). "CXCR4 and CXCL12 are both overexpressed in several diseases, including inflammatory disorders and cancer." (PMID 36499357, 2022).
cancer (continued). "Similar to other types of cancer, in EwS, CXCL12 was found to be essential for neovascularization and increased expression of CXCR4 was found to be associated with metastasis phenotype." (PMID 36230825, 2022). "Much research has indicated an inevitable role of CXCL12 in cancer development by triggering divergent pathways." (PMID 35408440, 2022). "These cells are expected to have the characteristics of cancer stem cells, and CXCL12 expression has been reported to be related to this resistance." (PMID 34976180, 2022). "The cancer-stroma interactions mediated by CXCL12/CXCR4 and E-selectin, which facilitate the formation of metastases in other anatomical sites, such as lymph nodes and lungs, are discussed elsewhere." (PMID 36568151, 2022). "CXC chemokine-12 (CXCL12) can specifically bind to CXC chemokine receptor 4 (CXCR4) and is closely associated with the progression of cancer via multiple signaling pathways." (PMID 35893797, 2022). "Cancer-activated fibroblasts (CAFs)-released CXCL12 chemokine activates CXCR4 and/or CXCR7 receptors and regulates PDAC cell proliferation, migration, and invasion." (PMID 36359736, 2022). "Taken together, these results suggest that the insulin-activated CXCL12/CXCR4 axis sustains a paracrine feedforward loop coupling cancer and stromal cells, thus fostering a motile phenotype in BCAHC-1 cells." (PMID 35672854, 2022). "Endothelial cells express both CXCR4 and ACKR3 receptors and secrete CXCL12, which facilitates the trafficking of cancer and immune cells between the bloodstream and the adjacent tissues." (PMID 35565443, 2022). "The chemotactic factor CXCL12 is identified at commonly seen sites of cancer metastases and in animal models, and it’s expressed in circulation oncocytes." (PMID 36211359, 2022). "So far, little is known about the clinicopathologic significance of CXCL12 expression in the plasma membrane of cancer cells in patients with LARC treated with nCRT." (PMID 34976180, 2022). "Cancers expressing CXCR4 metastasize to tissues with high levels of CXCL12, such as bone marrow, lymph nodes, lungs, and brain, suggesting that cancer cells utilize the CXCR4/CXCL12 axis to establish metastases." (PMID 35336029, 2022). "The expression of CXCL12 is upregulated and has a remarkable correlation with dismal prognosis in diverse cancers, e.g., breast cancer, pancreatic cancer, ovarian cancer, cervical carcer, and leukemias." (PMID 35408440, 2022). "Collectively, these, and potentially other CXCL12-dependent pathways, support the increased proliferation of cancer cells previously reported by our group and others." (PMID 35681470, 2022). "Then, using PDEs described as, TGFβ and LIF signals from cancer cells as well as TGFβ and CXCL12 molecules from CAFs release into the TME." (PMID 36171274, 2022). "The CXCL12/CXCR4 interaction promotes the early event of primary cancer cells expressing CXCR4 migrating towards CXCL12 to the liver." (PMID 35145271, 2022). "Significantly, the CXCL12/CXCR4/CXCR7 axis functionally contributes to cancer cell motility, invasiveness, and metastasis." (PMID 36568151, 2022). "In vivo, these cells metastasize because CXCR4-positive cancer cells selectively survive by an anti-apoptotic effect and by the secretion of CXCL12 by stellate liver cells." (PMID 35406582, 2022). "The levels of chemokine family members CXCR4 and CXCL-12, essential markers in the cancer microenvironment, were evaluated for protein and gene expressions." (PMID 36551144, 2022). "The CXCL12/CXCR4 axis has been reported to be involved in a variety of biofunctions of cancers via stimulating ERK1/2." (PMID 35860597, 2022). "Classically, CXCL12 recruits stromal cells in the lungs under normal conditions, and CXCR4 has been implicated in more than 20 human cancers." (PMID 35743888, 2022). "We focused on the plasma membrane expression of CXCL12 in cancer cells in the invasive front region of LARC after nCRT." (PMID 34976180, 2022).